RBP4 (retinol binding protein 4)
Diseases named in the same sentence as RBP4 in open-access papers (continued):
Sharing a sentence is not in itself a finding about the gene and the disease.
COVID-19 (continued). "In our study, we demonstrated significantly reduced RBP4 (p < 0.01) and vitamin A levels (p < 0.001) in the group of hospitalized COVID-19 patients in the acute phase of COVID-19 infection compared to convalescent patients after a mild course." (PMID 35631143, 2022). "In conclusion, to our knowledge, we have demonstrated for the first time that RBP4 and vitamin A levels are significantly decreased in severely ill COVID-19 patients." (PMID 35631143, 2022). "By taking the intersection of COVID-19/HCC genes and vitamin D-associated targets, we obtained seven overlapping genes (HMOX1, MB, TLR4, ALB, TTR, ACTA1 and RBP4) of vitamin D against COVID-19/HCC." (PMID 36275701, 2022). "Given these limitations, the consequences of reduced RBP4 and vitamin A plasma levels in COVID-19 patients warrant further investigation to explore potential therapeutic approaches of vitamin A supplementation during acute infection." (PMID 35631143, 2022). "Since SIgA is the predominant isoform of this antibody on mucosal surfaces, this study aimed to determine the relationship between the nutritional status of vitamin A, assessed by dietary vitamin A intake and RBP4 concentrations, and SIgA levels in COVID-19 outpatients." (PMID 38541764, 2024). "However, both retinol concentration and RBP4 synthesis can be compromised in acute inflammatory processes, as demonstrated in patients hospitalized for COVID-19." (PMID 38541764, 2024). "This suggests that more apo-RBP4 circulates in plasma in hospitalized COVID-19 patients." (PMID 35631143, 2022). "A possible explanation of the reduced RBP4 levels in critically ill COVID-19 patients could be SARS-CoV-2-related damage or an impairment of liver function." (PMID 35631143, 2022). "Overall, we conclude that RBP4 plasma levels are significantly reduced in critically ill COVID-19 patients during acute inflammation, and vitamin A levels are significantly reduced in patients with moderate/severe/critical illness during the acute phase of illness." (PMID 35631143, 2022). "Next, we further analyzed the possible binding of vitamin D with the seven COVID-19/HCC targets (HMOX1, MB, TLR4, ALB, TTR, ACTA1 and RBP4) identified previously and found that vitamin D only binds to MB and RBP4." (PMID 36275701, 2022). "An observational study examined that, compared to nonpatients, hospitalized COVID-19 patients had reduced VA plasma levels regardless of disease severity, and critically ill COVID-19 patients had reduced RBP4 plasma levels during their acute phase of illness." (PMID 38671384, 2024). "Moreover, we identified seven possible pharmacological targets of vitamin D against COVID-19/HCC, including HMOX1, MB, TLR4, ALB, TTR, ACTA1 and RBP4." (PMID 36275701, 2022). "Further, we identified seven overlapping genes of vitamin D against HCC and COVID-19 using the network pharmacology approach, and the anti-COVID-19/HCC effects of vitamin D may be modulated by these molecules or genes, including HMOX1, MB, TLR4, ALB, TTR, ACTA1 and RBP4." (PMID 36275701, 2022).
Hyperglycemia (14 papers, 2012 to 2025). An increased concentration of glucose in the blood. "A study on diabetic mice fed 0.2% of C3G as an addition to forage for 5 weeks revealed that mitigation of hyperglycemia and enhancement of insulin sensitivity was associated with reduction in retinol-binding protein 4 (RBP4) expression." (PMID 37298715, 2023). "Our data identify a longitudinal association between circulating RBP4 levels and IR, as well as hyperglycemia." (PMID 29759068, 2018). "Moreover, reducing circulating RBP4 levels effectively reversed β-cell dysfunction and ameliorated hyperglycemia in db/db mice." (PMID 38520616, 2024). "Further adjustment for life-style factors, BMI and MS component levels at baseline did not significantly attenuate the associations of RBP4 levels with follow-up IR, hyperglycemia, elevated TG or elevated blood pressure (Model 3) (P < 0.05)." (PMID 29759068, 2018). "As IR predisposes one to develop T2D, we found that subjects with the highest levels of RBP4 in childhood had the greatest risks of developing hyperglycemia during the 10-years follow-up phase, although there was a very low incidence of T2D after just 10 years of follow-up (at a mean age of 20.2)." (PMID 29759068, 2018). "Previous studies showed that the administration of cyanidin-3-glucoside ameliorates hyperglycemia in mice, possibly owing to the increased expression of GLUT-4 and decreased expression of RBP4." (PMID 26807159, 2016). "The same was observed in KK-Ay diabetic mice, where C3G improved hyperglycemia and insulin sensitivity by upregulating the expression of GLUT4 and downregulating the expression of retinol binding protein 4 (RBP4) and inflammatory indices (e.g., MCP-1 and TNF-α) in adipose tissue." (PMID 34204038, 2021).
renal dysfunction (14 papers, 2008 to 2024). "High RBP4 concentration is also independently associated with increased microalbuminuria risk, an early renal dysfunction indicator." (PMID 39583309, 2024). "The present meta-analysis revealed that circulating RBP4 levels were associated with renal dysfunction related to DM, which should be further investigated experimentally." (PMID 33082885, 2020). "It is assumed that renal dysfunction is closely linked to an increased occurrence of apo-RBP4 as well as RBP4-L and RBP4-LL in serum." (PMID 18752671, 2008). "In addition, a number of studies have indicated that circulating RBP4 concentrations were associated with renal dysfunction, and NAFLD has been found to be associated with decreased estimated glomerular filtration rate (eGFR) and/or microalbuminuria." (PMID 28931435, 2017). "Accordingly, this RBP4 fatty acid complex form might account for the high increase in urinary RBP4 in ADHF patients with renal dysfunction compared with those with normal renal dysfunction at hospitalization and the healthy group." (PMID 35216460, 2022). "Possible explanations regarding different concentrations or changes in RBP4 may include both ethnic and age differences (e.g., presence of renal dysfunction)." (PMID 32718041, 2020). "The pathogenic mechanism explaining the differences in RBP4 levels in DM patients with and without renal dysfunction might be associated with reduced catabolism and IR." (PMID 38711978, 2024). "Therefore, some scientists have proposed that liver dysfunction observed in preeclampsia is perhaps the major source of this increment in RBP4; renal dysfunction also complicates preeclampsia and may result in the excretion of less RBP4 in the urine." (PMID 36558360, 2022). "In fact, urinary excretion of RBP4 may be a useful marker for the detection of renal dysfunction." (PMID 32718041, 2020). "ROC analysis evidenced that combining RBP4 and TTR urine levels highly discriminated ADHF patients with renal dysfunction (AUC: 0.826, p < 0.001) and significantly predicted poor disease evolution over 18-month follow-up." (PMID 35216460, 2022). "These proteins consisted of several protein biomarkers related to respiratory health that were selected from literature, i.e. CC16, OPN and NF-κB, as well as of a number of potential urinary adjusters, i.e. β2M, RBP4 and MYO and a marker of renal dysfunction (HSA)." (PMID 33980897, 2021). "Elevated levels of RBP4 are observed in patients with renal dysfunction or in obese subjects and both conditions can be excluded as causing factors in our cohort." (PMID 32560166, 2020). "The level of RBP4 also increases during renal dysfunction but not during hepatic dysfunction." (PMID 33588861, 2021). "Thus, renal dysfunction is not enough toexplain the higher RBP4 concentrations in DCM." (PMID 39076230, 2022).
steatosis (14 papers, 2011 to 2026). Increased lipid within the cytoplasm of cells. "Steatosis and inflammation linked with metabolic alteration other than IR, determined RBP4 levels in HCV-infected patients." (PMID 33135589, 2020). "In this line, HCV-induced overexpression of an adipocytokine which takes part in steatogenesis, retinol binding protein 4 (RBP4), has been recently advocated as a possible expression of a virus-linked pathway to steatosis in CHC, largely unrelated to IR." (PMID 23956991, 2013). "Thus, steatosis and inflammation linked with metabolic alteration other than IR determined RBP4 levels in HCV-infected patients." (PMID 33135589, 2020). "We just shed a light in an explorative way on the association between levels and fibrosis and steatosis, by adjusting for gender, age, HOMA, adiponectin, RBP4, and visfatin." (PMID 40507178, 2025). "In conclusion, steatosis, sex, age, uric acid, NLR, and FIB-4 levels were associated with HCV-related RBP4 levels; BMI, triglycerides, and eGFR levels were associated with non-HCV-related RBP4 levels." (PMID 33135589, 2020). "In addition, ATF3 can improve hepatic macrophage glucolipid metabolism and reduce hepatocyte steatosis depending on retinol-binding protein 4 (RBP4) in the pathogenesis of MASH." (PMID 41479922, 2025). "Furthermore, we measured the serum retinol-binding protein 4 (RBP-4) levels as an indicator marker for the severity of steatosis and NASH progress." (PMID 26576191, 2015). "Liu found via animal experiments that the overexpression of RBP4 could aggravate liver mitochondrial dysfunction and promote steatosis in mice by impairing the oxidative capacity of the liver mitochondria, thereby suggesting that RBP4 is a possible target for liver fat accumulation." (PMID 36670387, 2023). "Interaction of FGF21/SHBG/RBP4 and adiponectin could reduce fatty acid synthesis and enhance FAO via activation of AMPK, and then resist steatosis and increase insulin sensitivity, but also could activate PPARα and inhibit NF-kB pathway." (PMID 36267567, 2022). "Studies have shown that serum RBP4 level is correlated with hepatocellular injury in patients with nonalcoholic fatty liver disease (NAFLD), and that it is also a new marker for virus-induced steatosis in patients infected with HCV having genotype 1." (PMID 22308156, 2011). "Furthermore, RBP4 is also strongly related to inflammation, and the progression of inflammation in the liver is a factor that influences the advancement of NAFLD because it exacerbates the transformation of simple steatosis into steatohepatitis." (PMID 36670387, 2023). "Taken together, steatosis, sex, age, uric acid, NLR, and FIB-4 levels were associated with HCV-related RBP4 levels; BMI, TG, and eGFR levels were associated with non-HCV-related RBP4 levels." (PMID 33135589, 2020). "Two of these studies compared RBP4 levels in patients with HCV with and without steatosis, three stratified patients with HCV by fibrosis stage [no, mild (F0–F2), and severe (F3–F4)], and four reported the correlation between HCV RNA levels and RBP4 concentrations." (PMID 39589965, 2024). "Steatosis thus is an HCV-related, but not a HCV-specific factor for RBP4 levels." (PMID 33135589, 2020).
gestational diabetes (13 papers, 2014 to 2026). Carbohydrate intolerance first diagnosed during pregnancy. "Plasma RBP4 concentrations may predict the risk for preeclampsia, pre-term delivery, and/or gestational diabetes." (PMID 35405978, 2022). "Former studies have identified that plasma RBP4 levels both in the first trimester and second trimester are dose-dependently associated with increased risk of gestational diabetes mellitus (GDM)." (PMID 34446012, 2021). "A recent meta-analysis also showed that increased RBP4 is a modest independent risk factor for women with gestational diabetes (GDM), similar to the results of case-control studies." (PMID 33679618, 2021). "Retinol-binding protein-4 (RBP4) has been reported to be potentially involved in the pathogenesis of gestational diabetes mellitus (GDM); however, the findings are inconsistent." (PMID 26975349, 2016). "However, two previously published meta-analyses on the association between RBP4 and the risk of gestational diabetes mellitus (GDM) have also reported higher levels of RBP4 among GDM cases." (PMID 36558360, 2022).
colon carcinoma (12 papers, 2017 to 2025). "For instance, RBP4 is elevated in colon cancer and associated with poor prognosis, whereas it is reduced in HCC and proposed as a potential diagnostic and prognostic biomarker." (PMID 40636697, 2025). "Downregulating STRA6 or RBP4 in colon cancer cells reduces the proliferation of cancer stem cells and sphere formation." (PMID 38913193, 2024). "Since RBP4 was originally identified as a circulation protein in plasma and showed a predictive role of in several malignancies including lung cancer and colon cancer, we were interested to investigate its role in GBM." (PMID 36632438, 2022). "Previous studies have shown that RBP4, as a member of the same family, its receptor is a strong transformation medium and drives malignant transformation in human breast and colon cancer cells." (PMID 35174205, 2022). "A recent study reported that downregulating RBP4 in colon cancer cells decreased the fraction of cancer stem cells, therefore we also tested the cellular effects of RBP4 in GBM cells." (PMID 36632438, 2022). "For instance, a high-fat diet drives LGR5 expression, ISC transformation, and tumorigenesis in mice colon cancer via an increase in vitamin A-bound serum retinol-binding protein 4-stimulated by retinoic acid 6 (RBP4-STRA6) signaling pathway." (PMID 33827616, 2021). "Previous studies demonstrated that another member, RBP4 and its receptor, are potent oncogenes in human breast and colon cancer cells that drive malignant transformation." (PMID 31598160, 2019). "Together, these data demonstrate a key role of STRA6 and RBP4 in the maintenance of colon cancer self-renewal and that this pathway is an important link through which consumption of HFD contributes to colon carcinogenesis." (PMID 28689994, 2017). "Downregulating STRA6 or RBP4 in colon cancer cells decreased the fraction of cancer stem cells and their sphere and tumor initiation frequency." (PMID 28689994, 2017). "RBP4 expression was elevated in colon cancer metastases compared with primary tumor and in patients who developed recurrent rectal cancer." (PMID 28689994, 2017). "A moderate positive correlation of RBP4 was observed with VEGFA in the primary colon cancer (r = 0.605) and with VEGFA (r = 0.631) and MYC (r = 0.499) in liver metastases." (PMID 28689994, 2017). "Knockdown of STRA6 or RBP4 in SW480 colon carcinoma cells decreased the levels of NANOG and SOX2." (PMID 28689994, 2017). "Our results show that RBP4 expression in tumors and not serum RBP4 levels were associated with aggressive forms of colon cancer." (PMID 28689994, 2017). "Downregulating STRA6 or RBP4 in colon cancer cells decreases CSC population and self-renewal." (PMID 28689994, 2017). "In colon cancer, RBP4 maintains the stemness of colon cancer stem cells by promoting the phosphorylation of STAT3, which affects colon cancer progression." (PMID 37313408, 2023). "To examine the effect of STRA6 and RBP4 on colon cancer growth we generated, using lentiviral short hairpin RNA (shRNA), SW480 colon adenocarcinoma cell lines in which STRA6 or RBP4 were stably downregulated." (PMID 28689994, 2017).
hepatocellular carcinoma (12 papers, 2009 to 2025). A malignant tumor that arises from hepatocytes. "The link between RBP4 and lymph node metastasis aligns with reports from hepatocellular carcinoma, where elevated RBP4 levels were associated with increased cell proliferation, invasiveness, and worse prognosis and TNM staging." (PMID 41007818, 2025). "It was reflected in the other reports demonstrating that enhanced RBP4 correlates with unfavorable prognosis in gastric carcinoma, hepatocellular carcinoma, and glioblastoma." (PMID 41007818, 2025). "Several studies have showed that RBP4 has a role in some types of cancers such as lung, pancreatic, ovarian, squamous cell, colorectal, prostate cancer and hepatocellular carcinoma." (PMID 28002423, 2016). "We performed immunohistochemical analysis on hepatocellular carcinoma (HCC) and adjacent tissues by using this anti‐RBP4 mAb." (PMID 34889069, 2022). "Similarly, hepatocellular carcinoma (HCC) patients with higher serum RBP4 levels exhibited poorer OS and DFS compared to those with lower serum RBP4 levels." (PMID 36632438, 2022). "It has also been reported that HMGA1 can bind the Rbp4 promoter and recruit the transcription factors steroidogenic factor 1 (SF-1) and liver receptor homolog 1 (LRH-1) to form an activation complex and induce Rbp4 transcription in Hepa1 mouse hepatoma cells." (PMID 29558965, 2018).
prediabetes (12 papers, 2013 to 2025). "In a 10-year prospective study, it was found that NGT with higher serum RBP4 was associated with new-onset prediabetes and T2DM." (PMID 37312059, 2023). "TTR was associated with prediabetes and TG level, whereas RBP4 was only associated with TG." (PMID 29747616, 2018). "Extensive epidemiological studies have shown that elevated levels of RBP4 are present in individuals with prediabetes and T2DM, with these levels being positively correlated with adipose tissue mass, metabolic disturbances, and cardiovascular disease." (PMID 40951890, 2025). "Our previous study revealed that serum RBP4 levels were significantly greater in patients with prediabetes than in patients without prediabetes, and serum RBP4 levels were associated with new T2DM after a 3-year follow-up." (PMID 38520616, 2024).
diabetic nephropathy (11 papers, 2016 to 2025). "Another study found that RBP4 concentration was positively associated with cognitive dysfunction in diabetic nephropathy patients with silent cerebral infarction." (PMID 37808505, 2023). "Second, RBP4 is a novel adipokine whose increased circulating levels are linked to IR in patients with diabetic kidney diseases." (PMID 33082885, 2020). "When patients were stratified by the underlying cause of CKD, univariate Cox regression analysis revealed a consistent inverse association between both baseline and longitudinal RBP4 quartiles and all-cause mortality across diabetic nephropathy (DN), glomerulonephritis (GN), and other etiologies." (PMID 40881125, 2025). "In agreement, studies indicate that RBP4 can be considered a biomarker of glomerular diseases, such as diabetic nephropathy, and proximal tubulopathies, such as Falconi syndrome." (PMID 40564893, 2025). "Furthermore, measurement of urinary afamin and RBP4 may serve as biomarkers for the accurate diagnosis of diabetic nephropathy and might help to reduce the burden associated with renal biopsy in patients with diabetic nephropathy." (PMID 36835525, 2023). "Besides, RBP4 may have a potential role in the pathogenesis of diabetic complications such as diabetic atherosclerosis and diabetic nephropathy." (PMID 37312059, 2023).